LINC01585 (long independently transcribed non-coding RNA 1585)
Gene: Long non-coding RNA gene on chromosome 15 (90,660,207 to 90,664,967, forward strand). Ensembl gene ENSG00000245479.
Diseases named in the same sentence as LINC01585 in open-access papers:
LINC01585 is named in the same sentence as 1 disease in open-access papers, as found by Europe PMC text mining. Sharing a sentence is not in itself a finding about the gene and the disease. The quoted sentences say what the papers report.
breast carcinoma (1 paper, 2020). "Such as LINC01585 binds to HuR in breast cancer, lncRNA OCC-1 also binds to HuR protein and induces ubiquitination through the binding of ubiquitin E3 ligase B-TrCP1 to HuR." (PMID 33050646, 2020). "Thus, LINC01585 depletion activates cAMP/CREB-related gene expression via recruitment of the NONO/CRTC complex, and promotes the proliferation of breast cancers." (PMID 33050646, 2020).